TOR1A (torsin family 1 member A)
Diseases named in the same sentence as TOR1A in open-access papers (continued):
Sharing a sentence is not in itself a finding about the gene and the disease.
Dystonia (continued). "In the present meta-analysis, that included a relatively large number of participants, we investigated the effect of TOR1A gene SNPs on the risk of dystonia, as well as on the risk of focal dystonia and its subtypes (cervical dystonia, blepharospasm and writer’s cramp)." (PMID 28081261, 2017). "The function of TorsinA and how TOR1A gene mutations lead to dystonia is poorly understood." (PMID 28081261, 2017). "Several lines of evidence suggest that an altered dopaminergic neurotransmission in Tor1a+/- mice may represent the endogenous predisposition for the observed intensified and prolonged dystonia-like movements in response to nerve injury." (PMID 27716431, 2016). "We questioned whether the observed striatal DA dysregulation was a cause or consequence to the development of post-crush dystonia-like movements in Tor1a+/- mice." (PMID 27716431, 2016). "Moreover, in Tor1a+/- mice the appearance of dystonia-like movements was associated with functional impairment of the gait pattern that was still present after 8 weeks indicating a predisposition to consolidate this movement disorder." (PMID 27716431, 2016). "DYT-TOR1A dystonia is caused by a heterozygous 3-bp GAG deletion in the Tor1a gene." (PMID 25120431, 2014). "DYT1 dystonia is caused by mutations in the TOR1A gene encoding TorsinA." (PMID 23028827, 2012). "While mutations of the TOR1A gene are responsible for early onset segmental dystonia that rarely involves laryngeal dystonia, polymorphisms in the same gene have been associated with adult-onset, primarily focal dystonia, including LD and even a decreased risk of developing dystonia." (PMID 38710818, 2024). "Interestingly, the frequency of a common coding polymorphism in TOR1A, p.Asp216His, was found to be increased in unaffected carriers and decreased in carriers with dystonia, and the penetrance associated with carrying this protective allele was further reduced to ~ 3%." (PMID 33876307, 2021). "These inheritance patterns of DYT1 dystonia suggest that complete loss of Tor1A function may cause lethality during embryogenesis and that heterozygous Tor1AΔE mutation may increase susceptibility to other genetic or environmental risk factors that caused severe symptoms." (PMID 27313903, 2016). "Thus, it is possible that mutations in GNAL and TOR1A genes may lead to dystonia via a common mechanism related to cAMP signaling." (PMID 25379658, 2014). "However, the reduced penetrance of some monogenic forms of dystonia, such as those due to mutations in TOR1A and THAP1, means that many apparently sporadic cases may also fall into this category." (PMID 23775978, 2013). "TOR1A-related dystonia generally responds well to bilateral globus pallidus interna deep brain stimulation (GPi-DBS) surgery." (PMID 40584247, 2025). "The disruption of THAP1 function impairs its regulatory control over TOR1A, potentially contributing to dystonia pathogenesis through a shared molecular pathway." (PMID 40724495, 2025). "In mouse models of dystonia, restoration of TOR1A function led to only partial recovery, suggesting that brain regions contribute to the modulation of dystonic symptoms." (PMID 40722357, 2025). "For instance, among early-onset dystonia syndromes, the detection of isolated generalised dystonia will first raise the suspicion of TOR1A- or THAP1-related dystonia, whereas the co-occurrence of myoclonus will suggest mutations in SGCE, ANO3, or KCTD17." (PMID 40649801, 2025). "To address this challenge, we used MoSeq, an unsupervised behavioral segmentation framework, to compare the continuous free behavior of control Tor1a +/+ mice and knockin Tor1a +/ΔE mutant mice in response to the anti-dystonia drug trihexyphenidyl." (PMID 42220653, 2025). "TOR1A, located on chromosome 9q34, was the first gene identified as responsible for isolated forms of dystonia." (PMID 40724495, 2025).
Dystonia (continued). "Neuroimaging studies64inDYT1(TOR1A) support the view that dystonia is a network and neurodevelopmental disorder, highlighting the role of imaging in elucidating its pathophysiology." (PMID 41429151, 2025). "Other dystonia genes with likely pathogenic or pathogenic variants were EIF2AK2 (n = 5 index patients), ANO3 (n = 2), EIF4A2 (n = 1), and TOR1A (n = 1) for genes causing isolated dystonia." (PMID 40533913, 2025). "Genetic dystonias encompass both situations where the primary symptom is dystonia (e.g., TOR1A, ANO3 mutations, etc.)and conditions where dystonia is a co-occurring feature of a more complex condition." (PMID 38612382, 2024). "The study assessed twelve participants using movement disorder specialist ratings of videotapes from patients with genetically determined dystonia (Tor1A and THAP1) who underwent GPi DBS." (PMID 38439837, 2024). "In the second case, with a 3-year follow-up, the genetic form of TOR1A suggested the GPi as a target due to the well-documented significant long-term outcomes in these genetic forms of isolated dystonia." (PMID 39126514, 2024). "Currently, genes THAP1, GNAL, TOR1A, and ANO3 are linked to isolated dystonia and have undergone extensive validation." (PMID 38612382, 2024). "TOR1A, the initially identified dystonia gene, was discovered about 25 years ago on human chromosome 9q34." (PMID 38612382, 2024). "Though it cannot be excluded that sensory deafferentation or dysfunction also plays a role in the development of these dystonic-like movements, the crushed ΔETorA rat is used as a humanised genetic TOR1A dystonia model." (PMID 37530804, 2023). "DYT- TOR1A dystonia is a hereditary nervous system movement disorder; other hereditary dystonias (such as DYT-THAP1, DYT-SGCE, and DYT-ATP1A3) are also caused by genetic mutations." (PMID 37638318, 2023). "Still, the genetic models, particularly manipulations of Tor1a in mice, have paved the way for testing the circuits and anatomical alterations in dystonia." (PMID 35821365, 2023). "In patients with DYT-TOR1A dystonia, mutations in the TOR1A gene impairs the binding of TorsinA to LAP1/LULL1, thereby compromising the ability of TorsinA to hydrolyze ATP." (PMID 37638318, 2023). "Although the exact mechanism of DYT- TOR1A dystonia is not yet fully understood, it is generally believed to involve complex interactions of factors such as genetics, protein deposition, signal transduction, and protein quality control systems." (PMID 37638318, 2023). "As an example of a genetic dystonia model, the ΔETorA rat model genetically mirrors the most common inherited DYT1 dystonia due to an overexpression of the mutated human TOR1A gene." (PMID 37530804, 2023). "Recently, researchers have modeled DYT- TOR1A dystonia using human patient-specific cholinergic motor neurons (MNs), which were generated by direct conversion of patient skin fibroblasts or induced pluripotent stem cell differentiation." (PMID 37638318, 2023). "With the exception of one, all were reported within the non-dystonia cohort, suggesting known contribution of incomplete penetrance in some known dystonia causing genes, such as THAP1 (DYT6) and TOR1A (DYT1)." (PMID 35925398, 2022). "We used electrophysiological and biochemical techniques to study synaptic alterations in the dorsal striatum of the Tor1a+/Δgag mouse model of DYT1 dystonia." (PMID 35420219, 2022). "We utilized electrophysiology recordings, immunohistochemistry, enzymatic activity assays, and Western blotting techniques to analyze in detail the cholinergic machinery in the dorsal striatum of the Tor1a+/− mouse model of DYT1 dystonia." (PMID 34173686, 2021).
Dystonia (continued). "Since the discovery that mutations in the TOR1A gene (i.e., DYT1) are responsible for most of the early-onset isolated dystonia cases, a growing number of genes linked to Mendelian forms of dystonia have been identified." (PMID 33051750, 2021). "Diffusion tensor imaging and tractography demonstrated an abnormal structural integrity of the white matter not only in patients with TOR1A and THAP1-related dystonia but also in symptomatic carriers of variants in the yet unconfirmed COL6A3 gene." (PMID 33486625, 2021). "A common form of primary early onset generalized dystonia is caused by 3 bp deletion (GAG) in the coding region of the TOR1A (DYT1) gene, which results in a defective protein called torsinA, whose role in dystonia pathology is unclear." (PMID 33799994, 2021). "Our results illustrate potential mechanisms underlying synaptic plasticity impairments in Tor1a+/- SPNs, demonstrating the close relationship between ER stress and plasticity abnormalities in dystonia, which could point out new directions for the treatment and prevention of dystonia." (PMID 34398825, 2021). "The results of the 13 patients who underwent genetic testing were as follows: 10 patients with idiopathic isolated dystonia, 2 patients with TOR1A (DYT1)-positive isolated dystonia, and 1 patient with THAP1 (DYT6)-positive isolated dystonia." (PMID 33716933, 2021). "This study suggests that Tor1a is required for normal ChIN development and survival and provides further evidence for a pivotal role for ChINs in the pathogenesis of dystonia." (PMID 33920757, 2021). "The finding that the density of spines is significantly reduced in Tor1a+/- SPNs further supports the notion that subtle functional and structural alterations in SPNs play important roles in neurological dysfunction in dystonia." (PMID 34398825, 2021). "Cholinergic dysfunction with significant increase in the vesicular acetylcholine transporter, used to assess cholinergic function in Alzheimer’s disease and Parkinson, has been described in the dorsal striatum of the Tor1a+/−mouse model of DYT1 dystonia." (PMID 34575134, 2021). "Here, we utilized a multidisciplinary approach to measure the possible changes in cholinergic markers, and their functional impact in the pathophysiology of dystonia, in the Tor1a null (Tor1a+/−) mouse model." (PMID 34173686, 2021). "Positional cloning identified that a mutation in TOR1A, encoding torsinA with an in-frame deletion of one glutamate residue, causes DYT1 dystonia, which is characterized by involuntary muscular contractions causing twisting movements." (PMID 33076344, 2020). "In the present work, we investigated the molecular mechanisms underlying DRD2 reduced levels and altered signaling in the striatum of DYT1 dystonia models, Tor1a+/−‐knock‐out and Tor1a∆gag/+‐knock‐in mice." (PMID 30552094, 2019). "In the Tor1a+/Δgag DYT1 dystonia mouse model, long-term potentiation (LTP) appeared prematurely in a critical developmental window in striatal spiny neurons (SPNs), while long-term depression (LTD) was never recorded." (PMID 29504938, 2018). "We performed a systematic review of Pubmed database to identify all available studies that reported genotype frequencies of TOR1A SNPs in dystonia." (PMID 28081261, 2017). "The aim of the present study was to systematically evaluate the effect of TOR1A gene SNPs on dystonia and its phenotypic subtypes regarding the body distribution." (PMID 28081261, 2017). "Only Tor1a+/- mice, however, demonstrate a centrally mediated component of dystonia-like movements as indicated by several biomarkers of striatal dopaminergic dysregulation and by showing a treatment response to DA depletion therapy." (PMID 27716431, 2016). "At later timepoints, during sensorimotor recovery, however, the severity of dystonia-like movements was more pronounced in mutant mice and only in Tor1a+/- mice sensitive to pharmacological modulation of central dopaminergic neurotransmission." (PMID 27716431, 2016).
Dystonia (continued). "DA neurotransmission changes in dystonia are likely just one step within a complex cascade of secondary maladaptive plasticity of the central network in Tor1a+/- mice." (PMID 27716431, 2016). "We describe an abnormal motor behavior in Tor1a+/- mice after peripheral nerve injury, that fits very well to the phenotypical description of dystonia based on the latest consensus definition." (PMID 27716431, 2016). "One of the loci, TOR1A/DYT1, is responsible for most cases of early-onset dystonia and has been the most studied form of dystonia." (PMID 25887123, 2015). "DYT1 dystonia is an inherited movement disorder caused by mutations in DYT1 (TOR1A), which codes for torsinA." (PMID 25799505, 2015). "Until the recent description of the genes CIZ1 (DYT23), ANO-3 (DYT24) and GNAL (DYT25) associated with CD families, only TOR1-A (DYT1) and THAP1 (DYT6) had been linked to isolated dystonia." (PMID 26110508, 2015). "In particular, five genes linked to dystonia appear to be involved upstream or downstream of DP-1 in the G1-S checkpoint pathway (ATM, CIZ1, TOR1A, THAP1 and TAF1)." (PMID 23849371, 2013). "DYT1 early-onset generalized torsion dystonia [Oppenheim’s dystonia; Online Mendelian Inheritance in Man (OMIM) identifier #128100, Dystonia 1] is a genetic dystonia caused by mutations in DYT1 (TOR1A) coding for torsinA with about 30% penetrance." (PMID 23967309, 2013). "Among the known human dystonia genes, the TOR1A gene, encoding the torsinA protein, is responsible for early-onset, torsion dystonia (DYT1) and has been the most studied type of dystonia." (PMID 22611399, 2012). "Early onset dystonia (EOD) is associated with a 3 bp-(ΔGAG) in-frame deletion in the TOR1A gene, which encodes for torsinA." (PMID 22988486, 2012). "Similarly, proper KMT2B functioning is essential for adequate expression of other dystonia-linked genes, such as THAP1 and TOR1A, which were reported to be downregulated in fibroblasts derived from patients with KMT2B pathogenic variants." (PMID 41518464, 2026). "This is underlined by the absence of the most frequent dystonia variant, p.E303del in TOR1A, which was excluded by prescreening." (PMID 40533913, 2025). "TorsinA is encoded by the TOR1A gene, a mutation that causes early-onset dystonia." (PMID 39940747, 2025). "The majority (n=43) were carriers of heterozygous variants in genes linked to dominantly inherited dystonia genes (ATP1A3, GCH1, SGCE, KMT2B, THAP1, TOR1A, and VPS16), while only one carrier of a homozygous PLA2G6 variant and one of compound-heterozygous PTS variants were identified." (PMID 40672488, 2025). "The first isolated dystonia gene,TOR1A, was identified almost 30 years ago." (PMID 41429151, 2025). "Although widely speculated, the relationship between DYT- TOR1A dystonia and LINC complex dysfunction remains unclear." (PMID 37638318, 2023). "Similarly, Purkinje cell firing was also irregular in an induced model of DYT1 dystonia that also utilized shRNA to knock down Tor1a in the cerebellum." (PMID 35821365, 2023). "The TOR1A dystonia group (n = 7) showed relative hypometabolism in the posterior putamina." (PMID 36445406, 2023). "As for mouse models of Dyt1/Tor1a gene mutation, including the Dyt1 knock-in, knockdown, and knockout model, most studies found that there was no overt dystonia manifestation." (PMID 36504662, 2022). "A study in a Tor1a mouse model of dystonia demonstrated impaired corticostriatal plasticity at MSNs that could be rescued through application of M1 mAChR-preferring antagonists." (PMID 33920757, 2021).
Dystonia (continued). "Recently, in the TOR1A‐dystonia mouse model, reduced expression of torsinB encoded by the paralog TOR1B was found to cause a dose‐dependent worsening of twisting, whereas torsinB overexpression was proven to rescue torsinA deficiency." (PMID 33816657, 2021). "Because the promotor of TOR1A contains two THAP1-binding sequences, it is tempting to speculate that some of the pathophysiological changes seen in DYT-TOR1A dystonia could similarly occur in DYT-THAP1 dystonia." (PMID 34095114, 2021). "In addition, increased AMPA receptor function and the reduction of NMDA/AMPA ratio in the postsynaptic of Tor1a+/- SPNs was observed, along with increased ER stress protein levels in striatum of Tor1a+/- DYT1 dystonia mice." (PMID 34398825, 2021). "Dystonia can be caused by numerous different causes and can generally be divided into acquired (e.g. brain lesion), inherited (e.g. due to TOR1A mutations, DYT-TOR1A/DYT1) or idiopathic (e.g. idiopathic cervical dystonia) causes." (PMID 33324912, 2020). "Since the discovery of the TOR1A gene and its connection to DYT-TOR1A dystonia (also known as DYT1 dystonia) in 1997, more than 200 genes linked to dystonia have been identified, with a significant increase in recent years due to the development of next-generation sequencing techniques." (PMID 31817799, 2019). "This neurological disorder can also be inherited: the most prevalent and severe inherited dystonia, DYT1 dystonia, is caused by a loss-of-function mutation in the DYT1/TOR1A gene that deletes a single glutamic acid residue (ΔE302/303, or ΔE) from the encoded torsinA protein." (PMID 31294022, 2019). "DYT1 dystonia is a hereditary early-onset movement disorder caused by mutations in TOR1A encoding the protein torsin A. Patients manifest with isolated dystonia in childhood or adolescence, usually without any other associated neurological abnormalities." (PMID 29948482, 2018). "The lack of replication and the inconsistency of the results among CGASs, meta- and pooled- analyses about TOR1A gene and dystonia could be attributed to a number of reasons." (PMID 28081261, 2017). "Development of dystonia-like movements after a standardized peripheral nerve crush lesion in wild type (wt) and Tor1a+/- mice, that express 50 % torsinA only, was assessed by scoring of hindlimb movements during tail suspension, by rotarod testing and by computer-assisted gait analysis." (PMID 27716431, 2016). "However, the frequency and duration of dystonia-like movements after nerve injury was higher in Tor1a+/- mutants as compared to wt mice with statistical significance at weeks four and eight after surgery (p < 0.05)." (PMID 27716431, 2016). "According to the Exome Aggregation Consortium database, the carrier frequency of this variant in Europeans is ∼4 times higher than the TOR1A [MIM 605204] c.904_906delGAG deletion (0.026%), which is by far the most common single mutation responsible for dystonia described to date." (PMID 26157024, 2015). "The inheritance pattern of DYT1 dystonia is autosomal dominant, and the genetic defect is an in-frame deletion of three nucleotides in the coding region of the TOR1A (DYT1) gene, leading to the loss of a single glutamic acid residue in the resulting protein, torsinA." (PMID 24260480, 2013). "In comparison to the human genes, dtorsin is most closely related to TOR1A, suggesting that investigation of the fly protein's function may be informative concerning the pathway(s) disrupted in human early onset dystonia." (PMID 22022556, 2011). "Similarly, TOR1A, traditionally implicated in cellular stress resilience, has been linked to NE defects, a finding reinforced by the identification of dysfunctional NPC components in dystonia." (PMID 41518464, 2026).